CSF1 (colony stimulating factor 1)
Diseases named in the same sentence as CSF1 in open-access papers (continued):
Sharing a sentence is not in itself a finding about the gene and the disease.
tumor (continued). "Tumor cells not only secrete high levels of colony-stimulating factor 1 (CSF-1) to independently recruit macrophages but also release the chemokine CCL2 in conjunction with Schwann cells, facilitating the infiltration of inflammatory monocytes via the CCL2/CCR2 axis." (PMID 38099290, 2023). "LIMK1 might trigger the chemoattraction of macrophages by tumour cells upon CSF-1 release and PKCζ activation, leading to tumour invasion and metastasis." (PMID 36899941, 2023). "CSF1 is a secretory ligand of CSF1R that is secreted by tumor cells." (PMID 37092846, 2023). "The expression of EGF by TAMs may be adversely affected by CSF-1 synthesized by tumor cells, which may enhance the metastatic potential of tumor cells." (PMID 38033495, 2023). "Moreover, the deletion of CSF1 also promoted the expansion of immunity generated against MC38 neoepitopes in tumor-bearing mice." (PMID 37505292, 2023). "In addition, in metastasis-associated macrophages, the deletion of Cav-1 can enhance VEGF-A/VEGFR1 activity, induce the downstream expression of MMP-9 and colony-stimulating factor-1 (CSF-1), and jointly promote angiogenesis and tumor metastatic growth." (PMID 37828916, 2023). "These infiltrated M-MDSCs could suppress NK cells activity, increase PD-1 expression to inhibit T cell proliferation and activate the CSF-1/CSF-1R pathway to polarize macrophages, which alter the tumor microenvironment to become pro-tumor growth." (PMID 37886177, 2023). "In the H22 tumor‐bearing mouse model, the CSF1/CSF1R inhibitor PLX3397 diminishes macrophage recruitment and M2 polarization and cooperates with immunotherapy by reshaping the tumor immune microenvironment and enhancing infiltration of CD8+T cells and mature DC cells." (PMID 38098217, 2023). "Hence, these findings suggest that the combination of CSF1/CSF1R signaling blockade with vaccine promoted an immune-permissive tumor microenvironment in the 4T1 tumor model." (PMID 37505292, 2023). "In addition, DHX9 facilitates the infiltration of macrophages into tumor tissues and their polarization to the immunosuppressive M2 type by upregulating colony-stimulating factor 1 (CSF1)." (PMID 38275375, 2023). "Nevertheless, it remains controversial whether CSF-1/CSF-1R signaling basically functions through regulating tumor immunity or tumor cell malignancy." (PMID 38067341, 2023). "In addition to a role in regulating tumor immunity, CSF-1/CSF-1R axis also plays a key role in supporting tumor cell survival, proliferation and enhancing motility." (PMID 35444953, 2022). "For instance, hypoxic tumor cells produce exosomes that are highly enriched in immunoregulatory cargos, including proteins and chemokines, such as colony-stimulating factor 1 (CSF-1), chemokine (C-C motif) ligand 2 (CCL2), ferritin H, ferritin L, and transforming growth factor β (TGFβ)." (PMID 36233088, 2022). "In addition, tumor cells promote the transformation of monocytes to M2 macrophages and inhibit the transformation to M1 macrophages through CSF1 signaling pathway." (PMID 36479092, 2022). "We found that only MES1-like tumor cells secreted CSF1 that interacted with CSF1R on TAMs." (PMID 35669791, 2022). "Although we rarely detected CSF1 split signals in the tumor cells of MTGCT, it is possible that these or new fusion genes may exist in these cases." (PMID 36320082, 2022). "Extensive overexpression of CSF-1 can be observed at the invasive edge of the various tumor, and it is involved in the polarization of M2 macrophages by interacting with its ligand CSF-1R; Its overexpression is also associated with a significant increase in metastasis." (PMID 36131942, 2022). "First, we treated mice with a neutralizing anti-CD115 antibody, which has been shown to alter the differentiation of tumor-associated macrophages due to impaired CSF1/CSF1R signaling, without modifying monocytes in the circulation." (PMID 36104342, 2022). "We showed that TAb2 tumor cells expressed higher levels of CSF1, VEGF, HGF and CXCL12." (PMID 35366939, 2022).
tumor (continued). "Meanwhile, tumor cells secrete CSF-1 to recruit more macrophages into the TME." (PMID 35672862, 2022). "Thus, cytokines/growth factors such as CSF-1 can mediate the interaction between epithelial tumor cells and inflammatory cells." (PMID 35326399, 2022). "Monocyte and macrophage infiltration into the tumor microenvironment may be facilitated by CSF-1/CSF-1R signaling and our previous studies indicate an expansion of TAMs in elderly vs. young mice." (PMID 35821822, 2022). "Indeed, ectopic CSF-1 overexpression by tumor cells attenuated the trametinib-induced reduction of CSF-1R+CD11c+ MDSCs and the infiltration of activated CD8+ T cells into the TME." (PMID 35292516, 2022). "Therefore, blockage of endogenous CSF-1/CSF-1R signaling can inhibit EC’s tumor growth and malignant progression." (PMID 35804859, 2022). "We then assessed whether the balance was altered during tumor growth in a murine mesothelioma model, a CSF-1 secreting cancer predominantly found in the elderly." (PMID 35821822, 2022). "TAMs can produce a variety of tumor-promoting factors, such as colony-stimulating factor-1 (CSF-1), so they might be attractive targets for remodeling immune responses within TME." (PMID 35814365, 2022). "Likewise, CD8+ T cells help shape the differentiation of TAMs, as Colony stimulating factor 1 (CSF1) release by exhausted CD8+ T cells was shown to favor antigen-presentation transcriptional programs in tumor-infiltrating monocytes." (PMID 35884605, 2022). "Notably, cytokines such as CCL2, CCL5, and CSF1 were found to be involved in the attraction of MDSCs to the tumor site." (PMID 36430577, 2022). "Neutralization of the chemokine CCL2 or inhibition of colony-stimulating factor-1 (CSF-1) receptor signaling prevent monocyte infiltration into the lymph node or tumor lesions, with a consequent reduced recruitment of tumor-specific T cells and damped antitumor responses." (PMID 36230990, 2022). "CSF-1/CSF-1R axis promoted the differentiation of MDSCs following the tumor progression." (PMID 35585567, 2022). "The role of the CSF-1R/CSF-1 axis has been studied in many cancer types, because tumor cells secrete CSF-1 to attract CSF-1R+ myeloid-derived cells to the tumor microenvironment to sustain tumor progression." (PMID 35115369, 2022). "For the polarization induced by PDAC-CM, given the complex composition of cytokines secreted by tumor cells, we noticed that CSF1 plays a key role in inducing the M2 polarization of macrophages in PDAC and CSF1 mRNA was highly expressed in PANC-1 and PANC-02 cells." (PMID 36324684, 2022). "The distinctive CSF1 expression in TSGCTs was scattered in many tumor cells." (PMID 36320082, 2022). "CSF-1 depletion reduces macrophage density, delays tumor progression, and inhibits metastasis." (PMID 36289653, 2022). "This was insufficient to meet predefined threshold criteria for efficacy, although the limited number of paired tumor biopsies examined did demonstrate the expected bioactivity, including a reduction in CSF1-dependent CD16-expressing monocytes, and increased CD4+ and CD8+ T cell numbers." (PMID 36077755, 2022). "The interaction of tumor cells and the matured macrophages cause the secretion of various factors, such as vascular endothelial growth factor (VEGF) and colony-stimulating factor–1 (CSF1), via tumor cells, promoting tumor growth and invasion." (PMID 36479071, 2022). "We hypothesized this would limit the anti-tumor activity of a ketogenic diet, which was tested by combining this diet with a CSF-1 inhibitor." (PMID 36428642, 2022). "We therefore sought to determine if CSF-1 inhibition could enhance the anti-tumor activity of a KD by normalizing this paradoxical increase in immune suppression." (PMID 36428642, 2022). "CSF1 participates in the recruitment of TAMs to tumor tissues and in the M2 polarization of TAMs." (PMID 36230744, 2022).
tumor (continued). "We therefore focused on tumor-CAF-macrophage interplay and hypothesized that blockade of CSF1R/CSF1 signaling at CAFs might reverse their protective role on tumor cells." (PMID 35315360, 2022). "Studies using mouse-xenograft models have shown that when CSF-1 signaling was blocked, TAMs number in the tumor area was significantly reduced, and tumor growth was inhibited, indicating that blocking CSF-1 signaling can attenuate tumor invasion and metastasis." (PMID 36105288, 2022). "TAMs can interpret tumor cells directly and lead to chemoresistance through the production of colony-stimulating factors (CSF)-1, increasing protease activity, inducing stemness of cancer cells through IL-6-mediated activation of STAT3 signals, and inducing enzymes involved in drug inactivation." (PMID 35658848, 2022). "Thus, CSF1 IHC is effective for the confirmative diagnosis of TSGCT if the location of the tumor is unusual." (PMID 36320082, 2022). "Notably, the upregulation of CSF1 and CCL18—as identified in the TME of ALK-positive tumors —increases type 2 (M2) tumor-associated macrophages (TAM) which have tumorigenic functions and are known to contribute to immune evasion." (PMID 34125345, 2022). "In the case of the CSF-1/Fms receptor, two aspects are relevant to tumor biology." (PMID 36555673, 2022). "Here, we found that trametinib treatment delays tumor initiation and progression of MAPK-pathway mutated HNC, while altering the heterogeneity of TME, in part via downregulating the expression of tumor-derived colony-stimulating factor-1 (CSF-1)." (PMID 35292516, 2022). "In the TME, low-dose RT causes the upregulation of colony-stimulating factor 1 (CSF1), a growth factor that is responsible for the differentiation, recruitment, and immunosuppressive properties of tumor-associated macrophages (TAMs) and myeloid-derived suppressor cells (MDSCs)." (PMID 35681654, 2022). "Inhibition of TAM recruitment by a CSF-1 may likely improve the ability of chemotherapeutic agents to reduce tumor progression and metastasis." (PMID 33613850, 2021). "CSF-1, as a tumor molecular marker, are highly expressed in a variety of tumors." (PMID 34729112, 2021). "Moreover, the CSF1/CSF1R pathway is a dominant regulator of macrophage differentiation and function, with studies showing that CSF1R inhibition can deplete tumor associated macrophages and improve T cell responses." (PMID 33796453, 2021). "The downstream effect blocked by CSF-1/CSF-1R hinders the growth of the tumor." (PMID 34447750, 2021). "However, apart from decreasing TAM frequencies at tumor sites, targeting the CSF1/ CSF1R axis can also repolarize TAMs to an ‘M1-like’ phenotype." (PMID 34638388, 2021). "Furthermore, CSF-1/CSF-1R signaling contributes to the conversion of TAMs from a tumor-suppressor phenotype to a tumor-promoter phenotype." (PMID 34178692, 2021). "Importantly, blockade of CSF-1 signaling also enhanced anti-tumor immunity and cytotoxic T cell infiltration to chemotherapy." (PMID 33968034, 2021). "MMTV-PyMT mice containing null recessive CSF1 (encodes M-CSF) had no change in primary tumor incidence or growth but had decreased formation of lung metastases." (PMID 34832904, 2021). "The humanized αCSF-1 also alleviated the effects of Abraxane on bone marrow cells in transgenic mice expressing human CSF-1, suggesting clinical relevance of αCSF-1 in prevention of bone marrow suppression in addition to its role in reducing tumor-infiltrating myeloid cells." (PMID 33537102, 2021). "TAMs can directly help tumor cells migrate through the paracrine ring between macrophages and tumor cells, which involves macrophages secreting epithelial growth factor (EGF) family ligands and tumor cells secreting CSF1, to improve the invasive characteristics of tumor cells." (PMID 34926295, 2021). "We evaluated the role of CSF1/CSF1R axis blockade in tumor-infiltrating immune subsets." (PMID 34067348, 2021).
tumor (continued). "Furthermore, it has been reported that CCL2, IL10, and CSF1 not only expressed in tumor cells, but also in macrophages." (PMID 34583750, 2021). "Tumor EVs from hypoxic conditions were shown to be enriched in chemokines and immunosuppressive factors, including colony stimulating factor 1 (CSF-1), chemokine ligand 2 (CCL2), and transforming growth factor beta (TGF-β), leading to macrophage chemotaxis and polarization into an M2-like phenotype." (PMID 34656117, 2021). "Indeed, the interaction between CSF1 on melanoma cells and its CSF1 receptor on macrophages shapes the tumor myeloid cell compartment toward immunosuppression by inducing the differentiation and accumulation of M2 TAM." (PMID 33947438, 2021). "CSF-1 is a cytokine involved in the polarization of macrophages into a tumor-supportive phenotype." (PMID 34204306, 2021). "In the excised tumor tissues, we examined the expression of circCDC45, miR-485-5p and CSF-1." (PMID 34627193, 2021). "Additionally, there is a positive feedback loop between macrophages and tumor cells: CSF-1 produced by tumor cells stimulates macrophage motility and secretion of EGF, which in turn supports chemotaxis of tumor cells into blood vessels." (PMID 33919517, 2021). "The tumor cells produce CSF-1 and C-C motif chemokine 2 (CCL2) and activate TAMs." (PMID 34281293, 2021). "In a tumor, tumor-derived CSF-1 and GM-CSF’s critical role in TAM proliferation is recognized." (PMID 33919979, 2021). "In tumor-associated macrophages (TAMs), OPN promotes programmed death ligand 1 (PD-L1) expression via activation of colony-stimulating factor 1 (CSF1) and its receptor, CSF1R-mediated signaling to facilitate migration and alternative activation of macrophages and to cause immunosuppressive effect." (PMID 33562077, 2021). "With the secretion of CSF-1, tumors are able to recruit CSF-1R-expressing macrophages and promote tumorigenesis by enhancing angiogenesis and metastases, resulting in poor survival in various types of tumor." (PMID 33230600, 2021). "Tumor-derived IL-6 and CSF-1 affect DC differentiation, promoting lineage commitment toward suppressive monocytes and VEGF inhibits DC maturation by suppressing NFκB signaling in hematopoietic progenitors as well as the tumor-derived TGF-β can inhibit antigen uptake." (PMID 33418996, 2021). "Notably, tumor cells can promote M2 polarization by expressing cytokines and growth factors including colony-stimulating factor 1 (CSF-1) and IL-4." (PMID 33916915, 2021). "We further investigated the mechanistic implication of TWIST1-CSF1 signaling to macrophage chemotaxis and polarization by showing a role of TWIST1 in the remodeling of OSCC tumor microenvironment via CSF1 regulation; this enhanced OSCC progression and metastasis competence in vitro and in vivo." (PMID 33466385, 2021). "Secondly, we did not evaluate the immunohistochemical expression of CSF-1, a major ligand of CSF-1R that influences the recruitment and polarization of M2 tumor-associated macrophages." (PMID 34830923, 2021). "For example, in breast tumors, CSF-1 may accelerate tumor progression and the transition to malignancy by recruiting TAM infiltration." (PMID 34178692, 2021). "Additionally, TCGA database analysis showed that the expression of CSF1 was upregulated in RCC and that CSF1 expression was higher in more advanced RCC tumor stages." (PMID 34722262, 2021). "CSF-1 is a potent macrophage chemoattractant produced by cancer cells to recruit macrophages expressing the CSF-R1 receptor and polarizes them towards the M2-tumor promoting subtype." (PMID 33922795, 2021). "However, protein and gene expression of both (TWIST1 and CSF1) are present after TWIST1 is reconstituted in the TWIST1 knockout tumor cells." (PMID 33466385, 2021).
tumor (continued). "Among these molecules, we focused on the cytokines associated with macrophage differentiation, including interleukins (IL), CC chemokine ligands (CCLs), and colony stimulating factors (CSFs); we found that CSF1 was markedly upregulated in the senescent tumor cells of three out of five patients." (PMID 33643790, 2021). "Moreover, the extent and intensity of CSF1 immunostaining and of the ELISA data showed that the senescent tumor cells were the major sources of CSF1." (PMID 33643790, 2021). "SPARC deletion promoted ROS generation and increased the production of pro-inflammatory and pro-angiogenic cytokines IL-6, CCL2, VEGF, and TNF-α as well as cytokines with pro-migratory ability, CCL3, CXCL2, CSF-1, and M-CSF, accompanied by greater tumor infiltration by mac1-positive TAMs." (PMID 34209679, 2021). "Additionally, HIFs regulate the production of Colony Stimulating Factor 1 (CSF1) in TNBCs, which recruits tumor-associated macrophages and myeloid-derived suppressor cells to the TME." (PMID 35582030, 2021). "We tested our hypotheses in MDA-MB-435 tumor-bearing nude mice and human CSF-1 knock-in mice treated with albumin-bound paclitaxel (Abraxane)." (PMID 33537102, 2021). "Some of these cells secrete chemokines (e.g., CCL2/MCP-1), cytokines (e.g., IL-4, IL-13) and growth factors (e.g., VEGF, CSF1/M-CSF and CSF2/GM-CSF) that trigger the recruitment of monocytes, and can promote cancer progression through the activation of tumor-associated macrophages (TAMs)." (PMID 33710603, 2021). "We, therefore, attempted to examine whether tumor-derived CSF1 or CCL2 was responsible for CXCL7 secretion." (PMID 34789744, 2021). "Co-amplification and co-overexpression of TWIST1, a transcriptional activator of epithelial-mesenchymal-transition (EMT), and colony-stimulating factor-1 (CSF1), a major chemotactic agent for tumor-associated macrophages (TAMs), were observed in metastatic OSCC cases." (PMID 33466385, 2021). "Colony-stimulating factor-1 (CSF1), also known as macrophage colony-stimulating factor, is the major chemotactic agent for TAMs that controls the production, recruitment, and survival of macrophages in tumor microenvironment." (PMID 33466385, 2021). "As shown in molecular investigations, the monocyte chemo-attractant protein (CCL2), the macrophage colony-stimulating factor (CSF-1), cytokines, and complement components, are well-known specific signaling molecules that recall inflammatory monocytes to the tumor sites." (PMID 34281293, 2021). "CSF1 produced by tumor cells inhibits the production of granulocytic chemokines by CAFs." (PMID 33670714, 2021). "Targeting CSF-1 signalling can reverse the pro-tumour phenotype of GAMs." (PMID 33803414, 2021). "Moreover, blocking CSF1 signaling with a CSF1 receptor inhibitor (PLX-3397) has also been shown to suppress tumor progression." (PMID 34722262, 2021). "The colony‐stimulating factor 1 (CSF‐1) pathway has sparked interest to block tumor recruitment of macrophages into TAMs,11 and multiple clinical trials are underway for agents targeting the CSF‐1 pathway for cancer treatment (NCT02829723, NCT02452424, NCT01349049)." (PMID 34027092, 2021). "This study further reported that both tumor cells and TAMs release CSF-1 and epidermal growth factor (EGF), respectively, which may interact which each other and facilitate the tumor cell migration." (PMID 34207035, 2021). "Efforts to deplete macrophages using small molecule inhibitors of the CSF-1/CSF-1R axis led to the unexpected finding that targeted populations could be instead repolarized towards anti-tumor phenotypes." (PMID 33924237, 2021). "It was observed that infiltration of MDSCs in tumor tissues increased after CSF-1R blockade, which may explain, to some extent, the limitations of the clinical efficacy of CSF-1 or CSF-1R inhibitors." (PMID 34178692, 2021). "SPON2 may indirectly induce M2-polarization through upregulating cytokines including IL10, CCL2 and CSF1 expression in tumor cells." (PMID 34583750, 2021).